CASP9 (caspase 9)
Diseases named in the same sentence as CASP9 in open-access papers (continued):
Sharing a sentence is not in itself a finding about the gene and the disease.
breast carcinoma (continued). "All the formulations containing nucleolipidic Ru(III)-complexes we have tested activate the mitochondrial apoptotic cell death pathway in breast cancer cells, as highlighted by a remarkable activation of caspase-9." (PMID 28349991, 2017). "Alpha-mangostin-induced ROS generation has also been observed to trigger mitochondria-mediated apoptotic cell death, including increased cytochrome c release and activation of caspase-9/caspase-3 cascade in MDA-MB-231 breast cancer cells." (PMID 28537893, 2017). "Our results are in line with another study which demonstrated that Manuka honey induces intrinsic or caspase-9 apoptotic pathway in breast cancer." (PMID 28399853, 2017). "Since SUM149PT and SUM1315MO2 cells have upregulated FASN and COX-2 pathways, we screened the effects of FASN inhibitor C75 and COX-2 inhibitor celecoxib or both in combination on the breast cancer cell lines using caspase 9 and caspase 3/7 assays." (PMID 27270654, 2016). "SVT inhibited the proliferation, altered the cell cycle and enhanced the induction of apoptosis of breast cancer cells by increasing the activities of caspase-3, caspase-8 and caspase-9." (PMID 26061816, 2015). "We showed that the inhibition of caspase-2 expression resulted in decreased activation of caspase-9, -3 and -7 after taxane application in breast cancer cells which implies that caspase-2 plays the role of an apical caspase in these cells." (PMID 25685064, 2015). "It was found that caspase-3/7, caspase-9 and caspase-8 were all activated significantly when the breast cancer cell lines MCF-7 and MDA-MB-231 were treated with SAMC." (PMID 25070343, 2014). "Given that initiator caspase-9 is an important mediator of apoptosis, we analyzed the ability of DPT-C9h to activate caspase-9 in the human breast cancer cell line HBCx5." (PMID 23637769, 2013). "Immunoblot analysis also revealed that FAE treatment induced a dose-dependent cleavage of Caspase 7, Caspase 8 and Caspase 9 in breast cancer cells, MCF-7 and T47D, suggesting the activation of mitochondria mediated pathway in apoptosis." (PMID 22792212, 2012). "In this study we report that α-TEA suppression of AKT via targeting IRS-1/PI3K leads to activation of proapoptotic Bad and caspase-9 in human breast cancer cells." (PMID 21119656, 2011). "Tumor COX-2, HER2 and estrogen receptor α (ER) expression and phosphorylation of Akt, BAD, and caspase-9 were analyzed immunohistochemically in 248 cases of breast cancer." (PMID 21078168, 2010). "In MCF-7 human breast cancer cells, caspase 8 activation appears to be due to the activation of caspase 9 within the apoptosome, as caspase 8 processing is inhibited by overexpression of the anti-apoptotic protein Bcl2." (PMID 19609365, 2009). "To further characterise the apoptosis observed in the RAMBAs-treated breast cancer cells, we used Western blot analysis to assess the activation and cleavage of apoptosis-related proteins, including Bad, caspase 9 and PARP." (PMID 17387344, 2007). "Moreover, the increase in caspase-9 expression was demonstrated after XAN treatment in a breast cancer mouse model, highlighting the potential role of XAN in the activation of the mitochondrial pathway of apoptosis." (PMID 40333735, 2025).
breast carcinoma (continued). "The present study found that PAB promoted apoptosis in canine mammary tumor cells and increased the expression of Bax, caspase-3, cleaved-caspase-9, and processed-caspase-3, and that the high catalytic activity of cysteine asparaginase-3 is a common initiator of apoptotic cell death." (PMID 41142571, 2025). "At the same time, the release of DAMPs, HMGB1 and ATP, were detected, suggesting that GSDME may mediate paclitaxel-induced pyroptosis in breast cancer cells through the caspase-9/caspase-3 pathway." (PMID 38954046, 2024). "Interestingly, both breast cancer cell lines incubated with a mix consisting of rGO and MG-132 showed increased percentages of active caspase-8 and active caspase-9 compared to examined cells incubated with rGO or with MG-132." (PMID 38791473, 2024). "In our study, activation of caspase-9 was detected only in the cells in 2D cultures, after 48 h of treatment with the complex, which highlights the role of the mitochondrial pathway in the apoptosis of breast cancer cells." (PMID 38739308, 2024). "As a prelude to testing the possible association between caspase-9 with metastasis in breast cancer, the expression of caspase-9 in TNBC and non-TNBC tumors was investigated in the stratified breast cancer patients from BCIP database." (PMID 38956424, 2024). "Interestingly, both breast cancer cell lines incubated with a mix consisting of rGO and MG-132 showed increased percentages of active caspase-8 and active caspase-9 compared to the examined cells incubated with only rGO or only with MG-132." (PMID 38791473, 2024). "Similarly, in the present study, 3HDT induced more γH2AX and 8-OHdG levels of DNA damage as well as apoptosis (annexin V, caspase 3, caspase 8, and caspase 9) in breast cancer cells than in normal cells, which was reverted by NAC pretreatment." (PMID 36982818, 2023). "Moreover, the isopropylated compounds in human breast carcinoma cells proved to be activators of apoptotic caspases that play a key role in both the initiation (caspase-9) and execution (caspase-3 and -7) phases of programmed cell death." (PMID 35209001, 2022). "In order to explore the relationship between CASP9 expression and immune infiltration in breast cancer, we used the TIMER to further analyze the association between CASP9 expression and immune infiltration levels in breast cancer." (PMID 36199443, 2022). "To further clarify the interaction between DEGs, we screened fifteen hub genes by constructing the PPI network, among which the expression of PSMC6, AURKB, CASP9, BAD, ZNF24, and SSX2IP was associated with OS in breast cancer patients, which attracted our attention." (PMID 36199443, 2022). "Besides, the protein expression level of cleaved-PARP, cleaved-caspase 3, cleaved-caspase 7 and cleaved-caspase 9 in the breast cancer cells increased after treated with compound 4f." (PMID 35551332, 2022). "Our results demonstrated that NKExos loaded with siBCL-2 exhibited a promising killing ability in ER+ breast cancer and led to induction of Annexin V, Caspase 3/7, and Caspase 9 over time, which clearly demonstrates the efficacy of siRNA NKExos for treatment of breast cancer." (PMID 34063475, 2021). "Thus, the role of caspase 8 in celecoxib-induced apoptosis in human lung cancer cells was shown, whereas apoptosis induced by another NSAID (FR122047) in MCF-7 breast cancer cells was even enhanced by siRNA knockdown of caspase-9." (PMID 33807213, 2021). "CASP9 expression has an apoptosis-inducing and anti-proliferative effect in breast cancer." (PMID 32513106, 2020).
breast carcinoma (continued). "Moreover, ECRG4 induced the formation of the Cytc/Apaf-1/caspase-9 apoptosome and promoted breast cancer cell apoptosis." (PMID 30918105, 2019). "Artemisinin treatment resulted in an enhanced cleavage of caspase 9 in MCF-7 breast cancer cells." (PMID 29246124, 2017). "Apoptosis-resistant cell lines, such as breast cancer MCF-7 cells, which are deficient in caspase-3, showed sensitivity to resveratrol treatment, and, interestingly, activation of caspase-9, as well as chromatin condensation, were detected in resveratrol-treated MCF-7 cells." (PMID 27657126, 2016). "Sequencing results revealed a candidate list of putative oncogenes and tumor suppressor genes, as well as canonical tumor suppressor genes such as caspase-9 and genes shown to be associated with HER2+ breast cancer such as the mitochondrial transporter protein SLC25A438." (PMID 25659579, 2015). "The functional DOX nanoparticles specifically could induce apoptosis of the drug-resistant breast cancer cells by releasing cytochrome C and initiating a cascade of caspase-9 and caspase-3 reactions." (PMID 25605018, 2015). "Therefore, our results put forward that caspases in general as well as selectively caspase-9 inhibition considerably blocked CFEA induced apoptosis in breast cancer cells." (PMID 26672742, 2015). "However, a dominant negative mutant of survivin, T34A, has been shown to be effective in treating xenografts of breast cancer by freeing up caspase 9 and thus promoting apoptosis." (PMID 15266313, 2004). "Mechanistically, GSDME may mediate paclitaxel and doxorubicin-induced pyroptosis in breast cancer cells through the caspase-9/caspase-3 pathway, activate anti-tumor immunity, and promote the efficacy of paclitaxel and anthracycline-based neoadjuvant chemotherapy." (PMID 38954046, 2024). "It has been shown that IFI6 plays anti-apoptosis roles in gastric and breast cancer cells, human myeloma cells and vascular endothelia cells, mainly through stabilizing mitochondrial membrane potential, inhibiting activation of caspase 3 and caspase 9, and decreasing Bax/Bcl-2." (PMID 34399768, 2021). "In current study, role of increased Cytochrome c release and caspase 9 cleavage in artemisinin induced apoptosis was found which validated previous reports suggesting involvement of mitochondrial pathway of apoptosis upon artemisinin treatment in MCF-7 breast cancer cells." (PMID 29246124, 2017). "In MCF-7, MCF-10A, HMEC, and MDA-MB 231 breast cancer cells, HSP (20–200μM) was found to increase ROS production, cyto-C release, Bax/Bcl-2 ratio, PARP cleavage, caspase-9, -3, -7, JNK, and sk1 activation, in addition to the activation of the ASK1/JNK pathway." (PMID 40427522, 2025). "The results revealed that XGE-1 exhibits a strong binding affinity for COX-2, with a binding energy of −9.4 kcal/mol, and a notable specificity for caspase 9, which plays a critical role in the proliferation of MCF-7 breast cancer cells." (PMID 41386876, 2025). "The most compelling finding is that simultaneously inhibiting caspase 9 (CASC9) and overexpressing miR-590-3p in the presence of lutein resulted in a greater suppression of breast cancer cell growth than either intervention alone." (PMID 41226811, 2025). "Intriguingly, METTL3 depletion has also been found to activate the CDKN1A/EMT pathway and m6A-BAX/caspase-9/-3/-8 cascade, thereby promoting proliferation, migration, and drug resistance in hormone receptor-positive HER2-negative breast cancer (HR+HER2-BC)." (PMID 40406121, 2025). "In breast cancer models, PEP-010 targets the interaction between caspase-9 and protein phosphatase 2A (PP2A), with preclinical in vivo studies demonstrating significant tumor regression, underscoring its therapeutic potential for aggressive cancers." (PMID 39795861, 2024). "Linoelaidic acid dramatically raised the levels of caspase 3 and caspase 9 protein expression, demonstrating that it can induce apoptosis in MCF-7 breast cancer cells." (PMID 37644076, 2023).
breast carcinoma (continued). "The breast cancer cell line MCF-7 had poor viability when miR-182-5p was inhibited, suggesting CASP9 upregulation is related to MCF-7 cell viability." (PMID 38007419, 2023). "In comparison to the control, the level of expression of cleaved caspase 9 proteins and cleaved caspase 3 protein were significantly upregulated after d-limonene treatment for 24 h in MCF7 breast cancer cells." (PMID 36307489, 2022). "The aim of the present experiment was the cytometric analysis of caspase 9 activity in MCF-7 and MDA-MB-231 breast cancer cells treated for 24 h with cisplatin and EDA-71 at concentrations of 1.5 and 3 μM." (PMID 36077839, 2022). "Using Western blotting, we found that HSF of KR upregulated caspase 9 and cytochrome C expression, indicating that HSF induces mitochondrion-mediated apoptosis in breast cancer cells." (PMID 36234972, 2022). "Our in vitro studies demonstrated that MY11 promoted breast cancer cell apoptosis by activating the NF-κB/PUMA/mitochondrial apoptosis pathway (including Bcl-2, Bax, and Caspase-9)." (PMID 35759135, 2022). "The concentration-dependent increase in the intrinsic pathway proteins like Apaf1, Caspase 9, Caspase 3, cleavage of PARP, Bax, and cytochrome c was observed in MCF7 breast cancer cells." (PMID 35615145, 2022). "For instance, this phytochemical triggers the intrinsic apoptotic pathway in CASP3-transfected breast cancer MCF-7 cells, based on the detection of activated CASP3 and CASP9, and PARP cleavage." (PMID 36497321, 2022). "It has been demonstrated that silybin stimulated under-expression of Bcl-2 and overexpression of Bax and Casp-8, Casp-9, and BID in MCF-7 breast cancer cells." (PMID 34094034, 2021). "Further, we proved PSD-A induced apoptotic cell death in breast cancer cells via analyzing expression of apoptotic hallmarks i.e. cleavage of caspase-9, caspase-3 and poly (ADP ribose) polymerase (PARP) along with total caspase-9, caspase-3 and PARP." (PMID 33013353, 2020). "The levels of cleaved caspase-3, cleaved caspase-9, and cleaved poly (ADP-ribose) polymerase (PARP) in human breast cancer cells exhibited similar trends." (PMID 32606352, 2020). "Treatment with cSBL cleaved the pro-caspase-9 and PARP in breast cancer cells, although the effects were relatively low in ZR-75-1." (PMID 30347895, 2018). "BP induces apoptosis in breast cancer cells, which was revealed by the TUNEL assay; the activation of caspase-9 and PARP was detected by western blot." (PMID 29370116, 2018). "Our data also showed that cleaved caspase-3, caspase-8, caspase-9 and poly ADP ribose polymerase-1 (PARP-1) were all increased in breast cancer cells." (PMID 28060760, 2017). "Our results showed that when pre-treated with PPARγ antagonists or PPARγ siRNA, both breast cancer cell lines suppressed PTER-ITC-induced apoptosis, as determined by annexin V/propidium iodide staining and cleaved caspase-9 expression." (PMID 25119466, 2014). "By both annexin V/PI staining and detection of cleavage of caspase 9, and PARP, it showed that compared with curcumin, HC increased the efficacy of induction of apoptosis of breast cancer cells." (PMID 22179587, 2012).
breast carcinoma (continued). "In a previous study of inflammation and breast cancer, we had found a positive correlation between COX-2 expression and increased phosphorylation of Akt, caspase-9 and BAD in breast tumors." (PMID 21078168, 2010). "Previous studies have indicated that histone deacetylase inhibitors (HDACi) can reduce tumor formation and induce intrinsic apoptosis in breast cancer cells by targeting HDAC5, which relies on the activation of the intrinsic apoptosis pathway involving caspase 9/3 signaling." (PMID 40781327, 2025). "Additional evidence for the interesting results outlined in this recent paper has also been reported by Syamet al.70 that showed apoptosis induction in breast cancer (MCF7) through stimulating the production of caspase-7, caspase-8, and caspase-9 using synthesized chalcone derivatives." (PMID 38110432, 2023). "The expression of key markers associated with proliferation (MKI67, PCNA, CCNB1, MYBL2, BUB1, CCND1), apoptosis (BCL2, CASP7, CASP8, CASP9, CASP3, BAX, APAF1), differentiation (CDH1, CD24, EPCAM, ESR1, NGFR, RUNX1), and breast cancer stemness (CD44, ITGA6, DNER, ALDH1A3, ABCG2, PROCR) was assessed." (PMID 35183258, 2022). "The qPCR analysis demonstrated that the synthesized nanoparticles desirably affected the gene expression in the studied breast cancer cell lines; resulting in down-regulation of the MMP-2, MMP-9, cyclin D, and cyclin E while up-regulation of caspase-3 and caspase-9." (PMID 35875198, 2022). "In particular, cleaved caspase 3 and cleaved caspase 9 were more significantly upregulated than caspase 3 and caspase 9, indicating that RBMS2 could induce breast cancer cells apoptosis." (PMID 35280673, 2022). "In human breast cancer cells, AITC induced mitochondrial-mediated apoptosis via cytochrome-c and release of apoptosis inducing factor and endonuclease G, as well as the activation of caspase-9 and caspase-3." (PMID 35163843, 2022). "It was confirmed by the analysis in Annexin V binding assay, as well as our observation of the increased caspase-8 and caspase-9 concentrations and decreased mitochondrial membrane potential in comparison with the untreated control in both MCF-7 and MDA-MB-231 breast cancer cells." (PMID 35456915, 2022). "However, when MCF-7 breast cancer cells are treated by delivering a ceramide kinase inhibitor into cellular mitochondria, the generated ceramide arrested MCF-7 at the G2/M phase and may have caused cell apoptosis by increasing DNA fragmentation and causing caspase-3 and caspase-9 cleavage." (PMID 35328500, 2022). "Our results are in line with another study which demonstrated that honey induces intrinsic or caspase-9 apoptotic pathway in breast cancer with no evident involvement of caspase-8 pathway." (PMID 35386216, 2022). "In breast cancer, YWHAEτ acts together with 1,3-DCQA (eicosanylquinic acid) to prevent the proliferation and metastasis of cancer cells through the Jak/PI3K/AKT and Raf/ERK pathways, and by inducing the Bad/Bax/caspase 9 apoptosis pathway." (PMID 34107979, 2021). "We showed that the activation of caspase 9 and caspase 3 was reduced in DUSP16-expressing NPC HK-1, CRC DLD-1, gastric cancer Nugc3, and breast cancer MDA-MB-231 cells, which was associated with reduced cytochrome c release in response to chemotherapeutic agents." (PMID 33863904, 2021).